RNU6-613P (RNA, U6 small nuclear 613, pseudogene)
Gene: Small nuclear RNA gene on chromosome 2 (229,894,346 to 229,894,453, forward strand). Ensembl gene ENSG00000222344.
Homologues: Orthologues: chimpanzee U6 (99% identical), guinea pig U6 (64% identical), pig U6 (63% identical), mouse Gm56440 (59% identical), mouse Gm25827 (58% identical). Paralogues in human: RNU6-1131P (74% identical), RNU6-12P (74% identical), RNU6-13P (74% identical), RNU6-26P (74% identical), RNU6-31P (74% identical), RNU6-32P (74% identical), RNU6-589P (74% identical), RNU6-737P (74% identical), RNU6-1 (73% identical), RNU6-1011P (73% identical), RNU6-1077P (73% identical), RNU6-1155P (73% identical), and 1287 more.